INS (insulin)
Diseases named in the same sentence as INS in open-access papers (continued):
Sharing a sentence is not in itself a finding about the gene and the disease.
Insulin resistance (continued). "Insulin-induced microvascular recruitment is blunted in insulin-resistant states such as obesity, and in turn contributes to insulin resistance." (PMID 26003324, 2015). "The correlation between insulin resistance and depression has also been established by one intervention study, wherein insulin sensitivity is improved by treating depression." (PMID 26053886, 2015). "TNF-α, which is mainly produced by macrophages and, to a lesser degree, by adipocytes in obese adipose tissue, can disrupt insulin/insulin-like growth factor signaling and contribute to insulin resistance." (PMID 26413130, 2015). "The present study was designed to provide a methodology for the C-peptide-based assessment of insulin secretion and β-cell responsiveness to glucose load in the Zucker fatty rat, a suitable experimental model of human obesity and insulin resistance." (PMID 25938808, 2015). "The increases in insulin AUC and hepatic insulin resistance found in the fructose group were unexpected." (PMID 26512691, 2015). "The defective IR signaling as indicated by the blunted insulin-induced Akt activation further corroborates the insulin resistance phenotype." (PMID 26103456, 2015). "Adiponectin is another adipocyte-derived peptide hormone, able to stimulate the sensitivity of peripheral tissues to insulin, thus acting to enhance insulin sensitivity and protect against conditions of insulin-resistance." (PMID 26560078, 2015). "Homeostasis model assessment of Insulin resistance (HOMA-IR) values were estimated as follows: [fasting blood glucose (mmol/L)*fasting insulin (mU/L)]/22.5." (PMID 25774226, 2015). "BCG administration significantly decreased epididymal white adipose tissue weight, serum insulin levels, and a homeostasis model assessment of insulin resistance." (PMID 26039731, 2015). "The oral treatment of SMC as well as metformin significantly decreased the glucose, insulin, and insulin resistance when compared with the HFD group of rats." (PMID 25650289, 2015). "Children who had both higher fasting insulin and weight at 5 years of age showed much higher levels of systolic blood pressures, fasting plasma glucose, the homeostasis model assessment for insulin resistance (HOMA-IR) and triglycerides at 10 years of age." (PMID 26047327, 2015). "Insulin resistance refers to impaired or failed intracellular transduction of the insulin-mediated signalling cascade in sensitive tissues, especially the liver, skeletal muscle, and adipose tissue." (PMID 26257839, 2015). "The HCHFD rats had reduced insulin sensitivity thus significant insulin resistance, but T2DM only occurred after the low-dose STZ injection." (PMID 26003803, 2015). "The pathogenesis of type 2 diabetes (T2D) is mediated by insulin resistance and abnormal insulin secretion." (PMID 26599349, 2015). "The observed effects were similar to those induced by insulin, suggesting potential benefits in the presence of insulin resistance." (PMID 25714093, 2015). "T2DM is preceded by a lengthy asymptomatic stage, termed prediabetes, which is characterized by mild hyperglycemia, insulin resistance, and early decrements in insulin secretory capacity." (PMID 26089953, 2015). "Insulin resistance is a state where insulin has less ability to mediate glucose homeostasis in its major target tissues such as liver, skeletal muscle and adipose tissue." (PMID 26715102, 2015). "In a recent study we reported the inflammatory cytokine-induced insulin resistance in human hepatocellular liver carcinoma cell line (HepG2), whereas suppression of its signaling pathway restored insulin sensitivity." (PMID 26247970, 2015). "Insulin resistance and abnormalities of insulin secretion in pancreatic ß-cells are the main defects that lead to T2DM." (PMID 26020947, 2015). "Only one of six randomized controlled trials to examine the effect of an exercise intervention on insulin and/or insulin resistance demonstrated statistically significant changes." (PMID 26339243, 2015).
Insulin resistance (continued). "The nilotinib group had significantly higher levels of fasting plasma glucose, insulin, C-peptide, insulin resistance, and total and LDL cholesterol than the imatinib and dasatinib groups." (PMID 26376678, 2015). "Serum adiponectin, leptin, F2-isoprostane, insulin, and lipid profile were estimated, and homeostatic model assessment of insulin resistance computed." (PMID 26273674, 2015). "Several potential mediators of insulin resistance have been identified, including defects in insulin signaling in insulin sensitive tissues." (PMID 25713323, 2015). "This was a cross-sectional study of 182 nondiabetic individuals (118 women and 64 men) who had measurement of 24 AAs and steady-state plasma glucose (SSPG) concentration (insulin resistance) using the insulin suppression test." (PMID 25952934, 2015). "The severe oxidative stress then intensifies insulin resistance and the continual declining of insulin sensitivity will lead to irritable increment of insulin." (PMID 25954750, 2015). "OA decreased blood glucose, improved insulin resistance, and enhanced insulin signaling by inhibition of ROS and anti-inflammatory effect in diabetic mice." (PMID 26843885, 2015). "Skeletal muscle also plays a major role in the pathology of insulin resistance as this tissue is important for whole body insulin-stimulated glucose removal." (PMID 25866760, 2015). "Mice on a chronic HFD gain more weight than their CD counterparts, develop insulin resistance, have aberrant responses to glucose tolerance tests and insulin tolerance tests." (PMID 26408147, 2015). "When calculating insulin resistance from serum glucose and insulin levels at the fasted state, it was higher in the AD-CON group than the Non-AD-CON group and all of the treatments lowered it to similar levels as Non-AD-CON." (PMID 25755673, 2015). "There was also a significant increase in insulin sensitivity and a decrease in insulin resistance (p < 0.01)." (PMID 26155596, 2015). "A group that combined DD with STZ treatment provided a model of advanced type-2 diabetes, which is characterized by defects in insulin secretion and insulin resistance." (PMID 26035391, 2015). "Studies have shown that this can cause local and systemic inflammation as well as an interruption in insulin action leading to severe insulin resistance in liver." (PMID 26618193, 2015). "In the ZFDM strain, fa/fa rats exhibit enlarged pancreatic islets at 7 weeks of age, in compensation for increased insulin demand due to severe insulin resistance." (PMID 25961052, 2015). "It is well recognized that insulin is directly related to the regulation of glucose level, and insulin resistance brings detrimental effects to cellular metabolism, leading to metabolic diseases, e.g. obesity." (PMID 25675096, 2015). "In mice with selective reduction of GLUT4 there is a reduction in insulin-stimulated glucose uptake in adipocytes and consequently insulin resistance." (PMID 26042666, 2015). "The homeostasis model assessment insulin resistance (HOMA2-IR) index values revealed that the exercise improved insulin sensitivity in the OLETF rats by 25%." (PMID 26172834, 2015). "We found significantly less pregnancy induced hypertension in metformin group as compared to insulin group, these findings being related to the effect of metformin on reducing endothelial activation and maternal inflammatory response to insulin resistance." (PMID 25874236, 2015). "Previous reports have shown that intravenous delivery of the human tissue kallikrein gene reduced blood pressure and plasma insulin levels in fructose-induced hypertensive rats with insulin resistance." (PMID 25918729, 2015). "Insulin resistance defines a condition in which tissue sensitivity to insulin action is decreased due to inhibited intracellular insulin signaling." (PMID 25887856, 2015).
Insulin resistance (continued). "In vivo insulin action was determined by conducting IAGT tests that detects diet-induced insulin resistance at more physiologically-relevant blood glucose levels than insulin tolerance tests." (PMID 26397111, 2015). "In insulin resistance, the ability of insulin to enhance glucose disposal in muscle and adipose tissue and to decrease gluconeogenesis in liver is impaired." (PMID 25951943, 2015). "Note that an increase in insulin secretion characterizes prediabetic patients and type 2 diabetic patients who have developed an insulin resistance." (PMID 26694479, 2015). "During normal pregnancy glucose metabolism and insulin production alters and results to insulin resistance." (PMID 26755467, 2015). "The mechanism can be elucidated by recent metabolomics studies which have found that BMI was positively associated with branched-chain amino acids (BCAA) which can interfere with insulin signaling and contribute to inducing insulin resistance." (PMID 26556598, 2015). "Obese children in our study showed significant elevated serum insulin and insulin resistance (HOMA/IR) than controls." (PMID 27275288, 2015). "Second, exogenous insulin administration is always followed by increased body weight, which is a key feature leading to insulin resistance, hyperinsulinemia, hyperglycemia, increased oxidative stress and proinflammation." (PMID 26537234, 2015). "The prevalence of high total serum cholesterol concentration was 7.6%, high LDL-C concentration was 10.1%, high fasting insulin concentration was 15.8%, and high insulin resistance was 13.8%." (PMID 26347891, 2015). "Our data demonstrate the critical roles of aPKCs in the regulation of hepatic insulin-sensitivity at gene expression level, and provide insights into the development of the insulin resistance and type 2 diabetes." (PMID 25822413, 2015). "As a consequence of insulin resistance combined with defects in insulin secretion, fasting and postprandial glucose levels were increased following sleep deprivation." (PMID 25834642, 2015). "The most likely mechanism for the diabetic onsets in patient group is insulin resistance and impaired insulin secretion in Japanese individuals with moderately high and increasing BMI." (PMID 26215867, 2015). "Increased hepatic ceramide has been suggested to be a major mechanism in the regulation of insulin resistance, and suppression of ceramide induction has been demonstrated to improve insulin signaling." (PMID 26648664, 2015). "At this stage, 0.4 mmol/L palmitate for 18 h significantly induced insulin resistance as revealed by Akt, p42/44 and p70S6K phosphorylation in response to insulin in all the vascular cells studied." (PMID 26055507, 2015). "Both surrogate markers used in our meta-analyses (HOMA index and fasting insulin) were classified to be inadequate in the assessment of insulin resistance in children and adolescents during a consensus conference on the topic in 2010." (PMID 26489667, 2015). "The major systemic event in T2DM, insulin resistance, imposes a requirement for higher levels of insulin." (PMID 26257839, 2015). "It is possible that temporary insulin resistance at the dinner time induced rapid elevation in glucose and insulin levels, and suppressed PTH secretion in Late-D." (PMID 26450680, 2015). "Understanding the mechanisms that lead to decreased mitochondrial activity in insulin-sensitive tissues is important for developing therapies to reverse insulin resistance." (PMID 25741283, 2015). "miRNA have been shown to play a crucial role in pancreatic development, insulin secretion and insulin resistance." (PMID 26110317, 2015). "Insulin resistance leads to decreased insulin signaling and, in turn, to decreased glucose transport into muscle." (PMID 25789156, 2015).
Insulin resistance (continued). "During fatty liver development, pathological accumulation of diacylglycerol stimulates the activation of PKCε by enhancing its translocation to the plasma membrane, thereby impairing canonical insulin signaling that in turn leads to hepatic insulin resistance." (PMID 26085100, 2015). "Insulin resistance is characterized by reduced glucose uptake by target tissues or cells (adipose, muscle, liver) owing to impaired insulin signaling transduction and/or glucose transporting ability." (PMID 26077651, 2015). "In TSOD mice, SRE treatment significantly decreased the glucose and insulin levels and increased the adiponectin level, implying an improvement in the insulin resistance." (PMID 25889885, 2015). "Enhanced glucose-stimulated insulin secretion is a common compensatory mechanism in β cells under an increased workload (e.g. insulin resistance), but compensation often turns into decompensation, resulting in the development of type 2 diabetes." (PMID 26139601, 2015). "Cardiac insulin resistance, characterized by impaired insulin stimulated glucose uptake into the myocardium, is concomitantly observed with peripheral insulin resistance in type 2 diabetic subjects." (PMID 26539824, 2015). "Other investigators demonstrated that the dietary curcumin supplement improved insulin resistance and hyperglycemia in diabetic mice with a simultaneous increase in plasma leptin and insulin levels." (PMID 25901155, 2015). "While the insulin level and insulin resistance rate were higher in reproductive aged PCOS than in healthy women, the difference of these risk factors decreased overtime." (PMID 26360602, 2015). "The major effector of RAS is angiotensin II (Ang II)—a critical promoter of insulin resistance because of its effect on insulin receptors and downstream signaling, which results in desensitization to insulin in metabolic tissues." (PMID 25993470, 2015). "Several models develop atherosclerosis after diet manipulations, despite inconsistent effects on blood glucose or insulin levels or on the development of insulin resistance." (PMID 25785279, 2015). "Despite increased serum insulin, plasma glucose levels also increased nearly 2-fold, indicating that the agonist increased insulin resistance nearly 10-fold, as assessed by HOMA-IR." (PMID 25849936, 2015). "It has been found that the age- and ceramide-dependent insulin resistance of rat hepatocytes coincides with a reduction of insulin-induced PLD activation, glucose uptake by the cells, and glycogen synthesis." (PMID 26089893, 2015). "T2D is characterized by hyperglycemia resulting from both pancreatic beta cell dysfunction with decreased insulin secretion and insulin resistance at target tissues." (PMID 26285759, 2015). "From the biological point of view, it is interesting that the PN approach models, for the first time, the experimentally well-known insulin-stimulated degradation of IR which plays a fundamental role in the insulin resistance and metabolic disorders." (PMID 26694479, 2015). "Insulin resistance affects many tissues and organs, either through impaired insulin signalling or through aberrant changes in both glucose and lipid (cholesterol and triacylglycerol) metabolism and concentrations in the blood." (PMID 26693205, 2015). "An interesting observation in our mouse study of glucocorticoid-induced insulin resistance is that the degree of resistance (glucose level) is nicely correlated with the increased endogenous insulin level." (PMID 27066265, 2015). "Since, the DM2 is also associated with change in body weight and alterations in serum insulin level or its sensitivity; we also measured the body weight, serum insulin level and insulin resistance in different controls as well as experimental mice." (PMID 26161865, 2015).
Insulin resistance (continued). "The hyperglycemia typically results from decreased insulin sensitivity (insulin resistance) in insulin-dependent tissues (such as skeletal muscle, liver and adipose tissues), which leads to hyperinsulinemia." (PMID 26363598, 2015). "Circulating chemerin has been also related to degree of glycemia and insulin resistance based on fasting glucose, glycated hemoglobin (HbA1C) and fasting insulin." (PMID 25933030, 2015). "In adipose tissue, obesity and insulin resistance are associated with lower levels of PGC-1α, whereas increased expression of PGC-1α in adipose tissue can promote an insulin sensitive, lean phenotype." (PMID 26176546, 2015). "Serum insulin levels and insulin resistance (HOMA IR) were similar in control group throughout the study period." (PMID 26436069, 2015). "One of the hallmarks of obesity is reduced vasoreactivity, increasing BP and insulin resistance through increased peripheral resistance and decreased delivery of insulin and glucose." (PMID 26003324, 2015). "Insulin is a likely candidate, known to be frequently increased in obese patients because of insulin resistance." (PMID 26618897, 2015). "Two uncontrolled observational studies investigated mean blood glucose (MBG) and mean daily insulin (MDI) changes from baseline after two days of oatmeal consumption in poorly controlled type 2 diabetic patients with insulin resistance." (PMID 26690472, 2015). "Insulin resistance also contributes to hyperandrogenism linked with PCOS and fasting insulin levels are correlated with androgen concentration as insulin is a strong stimulator of ovarian androgen production via the insulin receptors." (PMID 26690206, 2015). "Insulin resistance results from impairment of the insulin signaling pathway, but the molecular mechanisms are unclear." (PMID 25912041, 2015). "Type 2 diabetes or non-insulin-dependent or adult-onset results from the body’s ineffective use of insulin or as consequence of low amounts of insulin production from pancreatic β-cells or as peripheral insulin resistance." (PMID 28231209, 2015). "Significantly, AβO-injected mice failed to exhibit the expected suppression in acute food intake upon i.c.v. administration of insulin, indicating central insulin resistance (Fig4K)." (PMID 25617315, 2015). "Although β cells can compensate by increasing insulin production, approximately one-third of individuals with insulin resistance eventually develop β cell failure and diabetes." (PMID 26469762, 2015). "EPC levels in JIA patients were negatively correlated with index of insulin resistance (rho = -0.458, p = 0.021), endogenous insulin (rho = -0.472, p = 0.017), triglyceride (rho = -0.438, p = 0.029) and TNF-alpha levels (rho = -0.446, p = 0.026)." (PMID 25705139, 2015). "The secreted IL-1β binds to IL-1R and activates NF-κB and MAPK pathways, thereby impairing insulin signaling through the activation of IRS-1 in adipocytes leading to insulin resistance." (PMID 26779183, 2015). "Insulin resistance was assessed using a single blood test of fasting glucose and insulin levels, referred as derived homeostasis model assessment (HOMAIR)." (PMID 27747313, 2015). "Patients’ reluctance to initiate insulin, termed ‘Psychological Insulin Resistance’ (PIR) is an area of interest to researchers because health care professionals need to be informed on how to assist patients to overcome their barriers." (PMID 26913243, 2015). "At present, convincing evidence suggests that leucine benefits protein synthesis and improves insulin resistance and insulin sensitivity mainly through the mammalian target of rapamycin (mTOR) pathway." (PMID 26115673, 2015). "Human primary mature adipocytes were used as they represent a primary cell type for insulin action and the development of insulin resistance in obesity." (PMID 26064180, 2015).